INS (insulin)
Diseases named in the same sentence as INS in open-access papers (continued):
Sharing a sentence is not in itself a finding about the gene and the disease.
diabetes (continued). "An example is the role of the subcellular Zn distribution in Zn homeostasis in insulin producing pancreatic beta cells and the development of type 2 diabetes mellitus." (PMID 26911251, 2016). "Insulitis leads to the destruction of beta cells, while the onset of overt diabetes usually appears when approximately 90% of the pancreatic insulin is lost at around 10–14 weeks, although diabetes can develop up to 30 weeks of age." (PMID 27595114, 2016). "Many studies have identified specific miRNAs expression profiles of diabetes and described the critical roles of miRNAs in insulin secretion, pancreatic development and function and diabetic cardiovascular complications." (PMID 27137793, 2016). "Although as diabetes researchers we can put a large emphasis on understanding insulin secretory defects, aberrant glycaemia can also result from dysfunction in other islet cell types." (PMID 27508066, 2016). "An earlier investigation reported increased disease severity in critically ill patients with insulin-treated diabetes mellitus relative to all other patients on ICU admission." (PMID 27495247, 2016). "Mice that lacked glucagon receptors that had been treated with streptozotocin also developed diabetes after they had been treated with an insulin-blocking drug." (PMID 27092792, 2016). "When the mice undergoing such pancreatic reprogramming were treated with streptozotocin (STZ), the newly generated insulin-producing cells were able to ameliorate STZ-induced diabetes." (PMID 27526291, 2016). "Diabetes can be defined as a group of metabolic diseases characterized by hyperglycemia resulting from defects in insulin secretion, insulin action, or both." (PMID 27822481, 2016). "Of note, our findings are in line with previous studies in individuals with diabetes mellitus type 2 failing to show effects of beetroot juice supplementation on macrovascular or microvascular endothelial function, BP or insulin sensitivity." (PMID 27182277, 2016). "The pathogenesis of diabetes involves both genetic and environmental factors that adversely affect insulin secretion and regulation." (PMID 27733237, 2016). "Patients with autosomal dominant Mutant INS-gene induced Diabetes of Youth (MIDY) serve as an excellent model of insulin-deficient diabetes." (PMID 28702245, 2016). "In rats, malnutrition during lactation contributes to an altered metabolic state where the offspring developed diabetes and became insulin resistant." (PMID 26745373, 2016). "We performed a multivariate logistic regression analysis to determine the predictive markers for the progression to insulin-requiring diabetes." (PMID 27177031, 2016). "A first key challenge is the control of the released dose over time, which plays an essential role in medications that require a long-term therapy and/or a specific frequency of administration, as for instance insulin treatment for diabetes." (PMID 28773770, 2016). "In diabetes, the suppression or deficiency of MK2 improves glucose tolerance and insulin sensitivity in obese mice." (PMID 27376265, 2016). "Fat can increase the risks of getting diabetes and breast cancer by promoting the formation of insulin resistance and activating related signal passages of insulin/IGF, besides, they are prognostic dangerous factors." (PMID 27333326, 2016). "This illustrates the need for caution when using the MODY calculator for patients who were diagnosed before awareness of monogenic diabetes was widespread, as the calculator is very sensitive to the timing of insulin treatment." (PMID 27330718, 2016). "The db/db mice are an animal model of diabetes characterized by high plasma levels of NEFAs and insulin secretory defects of β-cells." (PMID 27366756, 2016). "All 22 of FT1D patients participating in this study displayed rapid diabetic ketoacidosis with little insulin secretion (F-CPR < 0.07 mM)." (PMID 26981545, 2016).
diabetes (continued). "HMGB-1 was shown to be increased at the onset of cystic fibrosis-related diabetes and was associated with indexes of glucose metabolism and body mass index in diabetes; however, treatment with insulin lowered its levels induced by glucose infusion." (PMID 27847406, 2016). "Diabetes mellitus is a chronic condition characterized by hyperglycemia, due to the metabolic impairment of insulin production/secretion and/or utilization in human body." (PMID 27618891, 2016). "We believe that the strict control of diabetes and long-term high-dose insulin therapy via HPA axis stimulation increase the TAV as an indirect indicator of the adrenal gland activation." (PMID 27563309, 2016). "T2DM, the far more common type of diabetes, is the state of insulin resistance whose cells fail to respond to insulin properly." (PMID 27069493, 2016). "Although high-intensity (>80% VO2max) exercise is effective in improving body composition, physical fitness, and insulin sensitivity its feasibility and efficacy in improving cardiometabolic markers for diabetes patients need to be established." (PMID 27073714, 2016). "Despite this, the extremely wide variation in LH rate reported so far in insulin-treated patients proves that no systematic educational program has been implemented world-wide to teach people with diabetes how to correctly inject insulin." (PMID 27213130, 2016). "A prospective study using a large number of subjects is required to establish the predictive markers for the progression to insulin-requiring diabetes in SPIDDM patients." (PMID 27177031, 2016). "Combination of oral drugs, and oral drugs with insulin has been used for better control of diabetes and diabetic vascular complications." (PMID 26739611, 2016). "A crucial component is the availability of a diabetes care specialist or endocrinologist experienced in intensive, tailored, modifiable insulin regimens who maintains close and careful monitoring during all phases of management." (PMID 27398228, 2016). "Liver cirrhosis promotes glucose intolerance and diabetes through various mechanisms including insulin resistance and impaired insulin secretion." (PMID 27882051, 2016). "Conversely, high lactate contribute to a higher insulin resistant status and a more malignant phenotype of cancer cells, promoting diabetes and cancer development and progression." (PMID 28077918, 2016). "Serum insulin levels were increased in offspring of obese mothers; however they were significantly lowered in the offspring with diabetes, in keeping with STZ treatment-induced pancreatic β-cell depletion." (PMID 27277011, 2016). "Despite substantial improvements in pharmacological diabetes therapy and technical advances in blood glucose monitoring and insulin application, a subset of patients fail to meet the target parameters." (PMID 27285580, 2016). "Therapeutic intervention to activate the glucagon-like peptide-1 receptor (GLP-1R) enhances glucose-dependent insulin secretion and improves energy balance in patients with type 2 diabetes mellitus." (PMID 26975372, 2016). "Epac proteins are widely expressed and have been implicated in multiple (patho)physiological processes including neuronal differentiation, cardiac function, insulin signaling and diabetes, chronic pain, and airway functioning (reviewed in refs 51 and 52)." (PMID 27808165, 2016). "Although, some trials have compared sucrose to glucose or starch in isocaloric exchange and demonstrated harm with regard to sucrose in insulin/glucose markers and prediabetes/diabetes." (PMID 27827899, 2016). "Diabetes results from the body being unable to produce enough insulin or respond to the insulin that is produced, which results in sugar accumulating in the blood." (PMID 27092792, 2016). "There have been several studies seeking predictive markers of the progression to insulin-requiring diabetes among patients with SPIDDM." (PMID 27177031, 2016).
diabetes (continued). "Patients in the highest quartile group were younger and more likely to be male, were current smokers and alcohol drinkers, had a shorter duration of diabetes, and were less likely to be insulin users." (PMID 27491472, 2016). "The final adjusted model (P < 0.001), which controlled for age, diabetes duration, insulin dose, insulin regimen, and socioeconomic status, slightly decreased the adherence-glycemic control association (estimate effect = −0.59, P = 0.003)." (PMID 27478510, 2016). "Accepted compounds were subjected to biological screening in a wide array of in vitro biological assays, covering the areas of diabetes/insulin secretion, osteoporosis, Alzheimer's disease, cell division and angiogenesis." (PMID 26978377, 2016). "In all patients, NEAT score showed an inverse correlation with waist circumference (r = −0.18, P = 0.044), serum TG (r = −0.17, P = 0.039), serum insulin (r = −0.263, P = 0.005), and duration of diabetes (r = −0.167, P = 0.042)." (PMID 26765475, 2016). "Although oral hypoglycemic agents and insulin are the cornerstones of treatment of diabetes and are effective in controlling hyperglycemia, they have prominent side effects and many limitations exist in their use." (PMID 26925100, 2016). "Insulin's stimulation of glucose uptake by binding to the IRK extracellular domain is compromised in diabetes." (PMID 27294151, 2016). "Disturbed insulin secretion is now recognized as a central player in the development of diabetes, a devastating disease which is reaching epidemic proportions." (PMID 27907065, 2016). "Average duration of diagnosed diabetes was 7.8 ± 6.3 years, average A1c was 7.4 ± 2.0, and 38% (12/32) were prescribed insulin." (PMID 27174496, 2016). "Studies show that treatment with intensive insulin therapy for 2.5 weeks can modify the natural history of diabetes." (PMID 27376154, 2016). "Another important difference between experimental and clinical T1DM is the common omission of insulin treatment in experimental diabetes leading to severe hyperglycemia ranging from roughly 17 to 25 mM blood glucose concentrations ([BG])." (PMID 26885531, 2016). "Recombinant production of human insulin was a real breakthrough because it opened a possibility for diabetes treatment at mass with human protein, an obvious step forward." (PMID 26983499, 2016). "New opportunities for research emerge from these results, notably on the prevalence of diabetes, the need for insulin analogues and use of real-world data for a new budget impact model." (PMID 27907034, 2016). "In conclusion, we propose diabetes teams to follow systematically the simple above-reported procedure for the diagnosis of LH at all insulin shot sites and to get it further implemented and hopefully progressively refined in large scale studies." (PMID 27213130, 2016). "It is well known that melanogenesis, progesterone-mediated oocyte maturation, GnRH and the insulin signaling pathway belong to the endocrine system, which is closely related to diabetes." (PMID 27677945, 2016). "Including these patients accounted for the increasing proportion of patients on insulin who included SMBG as part of their diabetes management." (PMID 26972690, 2016). "Early studies were done with Sprague Dawley rats artificially induced to have diabetes and showed the efficacy of insulin delivered via microneedle patches." (PMID 28773770, 2016). "In the univariate analyses, CKD was associated with high dioxin levels, age, gender, metabolic syndrome, diabetes mellitus, hypertension, and high insulin and uric acid levels." (PMID 26963719, 2016). "Previous studies reveal the use of different types and combinations of insulin for diabetes treatment, as well as a diverse role of insulin in different settings for a variety of patients with diabetes mellitus." (PMID 26759271, 2016).
diabetes (continued). "Achieving a metabolic state close to the physiological is a very challenging task and involves glucose monitoring, insulin treatment, diet management, controlled physical activity, and continuous education on diabetes management." (PMID 27170498, 2016). "Of the 146 (77.2 %) known to have diabetes mellitus, there were 12 (12.1 %) insulin users, and 133 (86 %) on oral medication for diabetes mellitus while one (1.9) was exclusively on diet control." (PMID 27145835, 2016). "In animal models of diabetes, several reports have identified a reduction in insulin sensitivity of dorsal root ganglion cells." (PMID 27514532, 2016). "We have previously demonstrated that oral administration of silkworm-produced CTB-insulin was capable of protecting 46% of NOD mice from diabetes." (PMID 26783749, 2016). "Thirteen were diagnosed with INS/PNDM (or with diabetes with onset during infancy) (2–4 and FB unpublished observations) before year 2010 and were treated with standard insulin therapy." (PMID 26239141, 2016). "Animal studies demonstrated that soluble fiber decreases the postprandial glucose curve and possibly ameliorates both the resistance and sensitivity to insulin in Zucker Diabetic Fatty rats." (PMID 27534844, 2016). "Diabetes mellitus is a chronic metabolic condition characterized by insufficient production of insulin or inability to use the insulin that the body produces, resulting in problems regulating blood sugar." (PMID 27526176, 2016). "Future experiments to determine the optimized conditions for the mechanism involved in zinc regulation for the optimal insulin production in β cells is a critical point for understanding clinical implications in not only Type-1 but Type-2 diabetes mellitus." (PMID 27983594, 2016). "Diabetes mellitus is a metabolic disorder of multiple etiologies characterized by hyperglycemia resulting from defects in insulin secretion, insulin action or a combination of both." (PMID 27253523, 2016). "Other major study, the Diabetes Control and Complications Trial (DCCT), found that intensive insulin treatment reduces the risk of development of DR and slows the progression of clinically important retinopathy." (PMID 27847639, 2016). "The treatments used among diabetes patients were insulin (n = 24), sulphonylureas (n = 23) or biguanides (n = 8) or both (n = 9), and diet (n = 18)." (PMID 26905276, 2016). "These adult human pancreas-derived MSCs have generated a great deal of interest owing to their potential use in the differentiation of insulin-producing cells for diabetes treatment." (PMID 27630717, 2016). "Involved in appropriate cellular respiration, depolarisation of the mitochondrial membrane potential has been observed in DRG sensory neurons in animal models of diabetes and is prevented by insulin administration." (PMID 27078166, 2016). "Strategies that seek to enhance insulin secretion and sensitivity are the cornerstone of diabetes treatment." (PMID 27478532, 2016). "This case demonstrates exacerbation of lactic acidosis in a patient with glycogenic hepatopathy treated for diabetic ketoacidosis with high dose insulin and dextrose." (PMID 27699071, 2016). "The registered nurses scored correctly on 76 % of the questions in the general diabetes subscale and 79 % of the questions in the insulin-use subscale." (PMID 27366112, 2016). "The proper functioning of β cells is reportedly disrupted by abnormal Ca2+ levels; for instance, insulin exocytosis from storage granules depends on the Ca2+ level, a process that is highly unregulated in diabetes." (PMID 27092078, 2016). "Type 1 diabetes mellitus (T1D) is a chronic disease characterized by an autoimmune response in which cellular immunity plays a pivotal role in the selective destruction of insulin-producing pancreatic beta (β) cells, thus leading to metabolic dysfunction." (PMID 26781648, 2016).
diabetes (continued). "GPR40 is a G protein-coupled receptor mediating free fatty acid-induced insulin secretion and thus plays a beneficial role in the improvement of diabetes." (PMID 27121981, 2016). "AdipoR1 and AdipoR2 regulate metabolic gene expression and insulin sensitivity in insulin target tissues, and are important in the pathophysiology of insulin resistance and diabetes." (PMID 26993044, 2016). "Diabetes mellitus can be classified into two main types, type 1 and type 2, with type 1 resulting from the body's failure to produce insulin, and requires one to be injected with insulin." (PMID 27294153, 2016). "On the other hand, high sodium intake improved insulin sensitivity, especially in individuals with diabetes." (PMID 28066329, 2016). "It has also been suggested that increased basal insulin secretion leads to increased food consumption, obesity and diabetes." (PMID 26986474, 2016). "The following possible confounders were separately entered as independent variables into model 1 (model 2): plasma fasting glucose, plasma fasting insulin, time since diagnosis of diabetes, heart rate, SBP, DBP, myocardial steatosis, us-CRP and NT pro-BNP." (PMID 27874027, 2016). "The aim of regenerative medicine for diabetes is to develop a renewable and safe source of stem cells to replenish the damaged cells, providing the patients with a long term source of insulin producing cells." (PMID 27400873, 2016). "Based on reported preference for different health states, these results suggest that changes in HbA1c levels, insulin regimen and body weight are all likely to affect HRQoL for patients with diabetes." (PMID 26801908, 2016). "Diabetes mellitus (DM) is an endocrine disease characterized by a deficit in the production of insulin with consequent alteration of the process of assimilation, metabolism, and balance of blood glucose concentration." (PMID 27478847, 2016). "At the onset of diabetes two main processes are involved in its pathogenesis: progressive decline in pancreatic islets function and reduced insulin sensitivity in peripheral tissues." (PMID 26697506, 2016). "Hypoglycaemia is a common and potentially life threatening consequence of insulin and sulphonylurea treated Diabetes." (PMID 26893294, 2016). "Because of this important role on insulin sensitivity, adiponectin is currently one of the strongest biochemical predictors of type 2 diabetes mellitus." (PMID 27189377, 2016). "These include insulin resistance, impaired insulin secretion, diabetes, hypertension, inflammation and dyslipidemia." (PMID 26891322, 2016). "Currently, the main and effective treatment for diabetes is the use of insulin and hypoglycemic agents." (PMID 28197508, 2016). "Diabetes mellitus is defined as a dysregulation of glucose metabolism due to improper insulin secretion, reduced insulin efficacy or both." (PMID 26955508, 2016). "Distribution of differences in numbers of diabetes treatments prescribed between baseline and follow-up in Telescot diabetes trial participants by trial arm and initiation of insulin during follow-up." (PMID 27458809, 2016). "Failure of the body to produce or response to insulin leads to the development of diabetes mellitus." (PMID 27625609, 2016). "A definition by the World Health Organization states that: “Diabetes is a chronic disease that occurs either from insufficient production of insulin by the pancreas or ineffective use of produced insulin”." (PMID 26964572, 2016). "Although this study has some limitations, mainly regarding islet stimulation induction and sample size, in conclusion, mice with disrupted Wfs1 gene had fewer pancreatic islets and defective insulin secretion explaining their diabetes‐like phenotype." (PMID 27053292, 2016). "The treatment of diabetes with insulin induces accumulation of lipids in adipose, muscle, and other peripheral tissues." (PMID 27055280, 2016).